FOXP3 (forkhead box P3)
Diseases named in the same sentence as FOXP3 in open-access papers (continued):
Sharing a sentence is not in itself a finding about the gene and the disease.
tumor (continued). "Furthermore, the infiltration of pDCs into tumors leads to reduced levels of IFN-α, sustaining the expansion of intratumoral Foxp3+ Tregs, thereby promoting immune tolerance and tumor progression." (PMID 38512518, 2024). "The CellphoneDB analysis of ligand-receptor pairs showed that the interaction networks between UPP1high tumor cells and FOXP3+ Tregs/LAG3 + PDCD1 + CD8 + T cells were involved with numerous immune checkpoints, including CD274/PDCD1LG2_PDCD1, FGL1_LAG3, and NECTIN_TIGIT." (PMID 38331898, 2024). "However, similar to Foxp3+CD4+ T cells data, the presence of IL17A+CD4+ T cells in the tumour microenvironment is associated with potential anti-tumour, as well as pro-tumourigenic effects due to their plasticity." (PMID 39409156, 2024). "Importantly, we also noted that although there were general increases in the absolute numbers of cytokine-producing exTregs and Foxp3+ RFP+ Tregs in both tumor and the spleen, it was the “fragile” cytokine-producing Foxp3+ Tregs which were more numerous." (PMID 38995700, 2024). "The findings highlight the complexity of FoxP3+ Tregs function in various tumor stages, which may relate to the fact that Tregs mainly suppress pro-tumor inflammation in early stages of tumors, but hinder tumor killing by effector T cells in advanced stages." (PMID 38509593, 2024). "The identification of CD137 + Eomes + FoxP3+/- T cells could be a key element in the selective activation of the most anti-tumor cells in the HPV + OSC microenvironment." (PMID 38355394, 2024). "For example, Lactobacillus reuteri increases the production of Foxp3, a Treg marker, which suppresses tumor development by limiting inflammatory pathways that may contribute to tumor progression and reduce systemic inflammation." (PMID 39767682, 2024). "Moreover, mouse tumor growth and proliferation were inhibited, and the number of FOXP3+CD25+ T cells was increased, while ferroptosis was enhanced after LINC00942 knockdown in vivo." (PMID 38353724, 2024). "They found that the patients with a low density of tumor-infiltrating FOXP3 and CD8-positive T lymphocytes, neutrophils, and mast cells and the patients with a high density of natural killer cells showed a significantly longer overall survival and progression-free survival." (PMID 38611634, 2024). "Overall CD8+ T cell infiltration was associated with clinical benefit (P = 0.026) in contrast to tumor infiltration with regulatory T cells (FoxP3+) or CD8+/FoxP3 ratio, which were not." (PMID 38653864, 2024). "For other inflammatory cells, such as memory T cells (CD45R0+) and cytotoxic (CD8+) and regulatory T cells (FoxP3+), higher infiltration of inflammatory cells was present in the stromal tumor compartment than in the epithelial tumor compartment, respectively, in the identical cohort." (PMID 38397442, 2024). "Because CD20+ B cells and CD4+ CD38+ T cells promote cytotoxic T cells for killing tumor cells, the observed distribution pattern indicates that FOXP3+ Tregs and CD66+ neutrophils might synergistically attenuate this process." (PMID 38674427, 2024). "The fluorescence intensities of MCU, FOXP3, and TGFb1 were notably lower in the non-tumor group." (PMID 38632642, 2024). "Interestingly, the tumor growth significantly correlated with the intra-tumoral frequency of the CD25+FOXP3+ regulatory T cells (Treg)." (PMID 38385162, 2024). "Importantly, the A. vulgaris extract remarkably decreased the percentage of CD3+CD25+Foxp3+ regulatory T cells (Tregs) in the spleens of tumor-bearing mice." (PMID 38920557, 2024). "This suggests that FOXP3, a Treg biomarker, may play an intriguing role in immune evasion induced by tumor cells." (PMID 38331927, 2024). "Our study also unveils that elevated zinc intake heightened the presence of Foxp3+ Treg cells and upregulated PD-1+ T cells within the tumor microenvironment, with T-cell-deficient (RAG1−/−) and Foxp3-depleted mice mitigating the tumor-promoting effects of zinc." (PMID 39247196, 2024).
tumor (continued). "The recurrent group exhibited an enrichment of Pseudomonas, Staphylococcus, Corynebacterium and Acinetobacter, and the tumor stroma showed increased infiltration of FoxP3+ regulatory T cells (FoxP3+ Treg), which has been shown to promote immune escape and tumor growth through various mechanisms." (PMID 39703512, 2024). "In addition, The Treg density of FOXP3 in tumor tissue is higher than that in normal colon mucosa, and its increased expression is associated with poor CRC survival rate." (PMID 38919615, 2024). "Additionally, Treg, CD4+, CD25+, and Forkhead box protein P3 (FoxP3)+ have been identified as critical inhibitors of Th1 and cytotoxic T lymphocyte responses, which are significant means of tumor evasion in many cancers." (PMID 39421442, 2024). "FOXP3’s role in cancer cells may function in a broader role to promote immune resistance in cancer cells as well as instigating tumor metastases." (PMID 39099201, 2024). "Furthermore, specific pharmacological technologies should be developed for treatment because the Foxp3 pathway is currently underutilized in the development of anti-tumor therapies, as indicated by available experimental evidence." (PMID 38919615, 2024). "Therefore, it can be said that increasing the expression of the FOXP3 can increase the number of Treg cells, which in turn suppresses the immune response against the tumor, which results in the progression of cancer." (PMID 39315286, 2024). "Furthermore, studies demonstrated that the patient’s tumor/stromal ratio and CD8+/Foxp3+ ratio were independent risk factors for prognosis." (PMID 38983929, 2024). "The role of FoxP3+ Tregs in patients with tumors and their impact on prognosis is a contentious topic that may be affected by the tumor’s clinical stage." (PMID 38509593, 2024). "In this context, FOXP3 plays an integral role in the development and differentiation of Tregs and in mediating tumor immune evasion, making it an effective target for identifying Tregs in the tumor microenvironment." (PMID 39198311, 2024). "We noted that a transcription factor, basic leucine zipper ATF-like transcription factor (Batf), which has been shown to play a crucial role for Treg development in the tumor microenvironment, was expressed on the Tregs_Foxp3 cluster that was remarkably expanded in dKO cells." (PMID 39405120, 2024). "This has prompted us to investigate the characteristics of c-FOXP3+ tumor epithelial cells." (PMID 38047300, 2024). "Tregs could suppress many antitumor immune cell subsets to promote tumor growth, while FOXP3 is reported a master regulator in the development and function of Tregs." (PMID 39042313, 2024). "Tumor-induced Treg cells 14 contributed to tumor progression by expressing not only a plethora of genes with well-established immune suppressive function, but also genes that support a committed Foxp3+ Treg phenotype 35." (PMID 39113693, 2024). "Of note, endogenous CD4+CD25+FoxP3+ T cells found within the tumor expressed both NRP1 and Plexin-A1 as well as TGFβR1-2, indicating that this subset of T cells might be modulated differently from CD8+ T cells." (PMID 38609390, 2024). "The panel consisted of primary antibodies against various immune cells, including CD20+ B cells, CD3+ T cells, CD8+ T cells, CD68+ macrophages (Mø), CD163+ tumor-associated macrophages (TAMs), CD14+ monocytes (M), CD15+ neutrophils (NE), FOXP3+ Treg cells, and the proliferation marker Ki67." (PMID 38164148, 2024). "Foxp3-positive cells were observed around the invasive front of the tumor." (PMID 38438903, 2024). "However, tumor-bearing CD11c:DTA mice exhibited a reduced proportion of CD4+Foxp3+ Treg cells and Teff cells in TdLNs." (PMID 39206204, 2024). "This indicates that USP20 may play a role in regulating the autoimmune process and may be a potential target for inhibiting FOXP3-induced tumor immune escape." (PMID 38806474, 2024).
tumor (continued). "Further, dual treatment with both CD155 and CD73 blocking antibodies had increased intracranial tumor infiltrates of NKp46+GzB+ NK cells and CD3 + T cells, without significant upregulation of PD-1 + T cells, LAG-3 or FoxP3+ Tregs, further justifying targeting of both tumor antigens." (PMID 38429294, 2024). "The significance of nuclear FoxP3 expression in tumor cells and hepatocytes is unclear." (PMID 39563958, 2024). "Nuclear FoxP3 staining was also detected in tumor cells, hepatocytes, and CD45R0 cells." (PMID 39563958, 2024). "FOXP3, a marker of Tregs, was highly expressed in tumor tissues from PC patients." (PMID 39425009, 2024). "Removing Foxp3+Treg cells from tumor tissues can enhance anti-tumor immunity, hence a combined strategy of blocking PD-L1/PD-1 while depleting Tregs might show promise in improving treatment outcomes for these patients." (PMID 38762484, 2024). "While the interaction with the major histocompatibility complex (MHC II) may induce macrophages and CD8+ activation against tumor cells, it may also lead to differentiation into regulatory T cells (such as FOXP3+ cells) and inhibit the immune response." (PMID 38787209, 2024). "The quantity of Foxp3+ regulatory T cells was related to lymph node metastasis (r = 0.858; P = 0.002), and the ratio of CD8 to Treg was strongly negatively associated with tumor size." (PMID 39290709, 2024). "The increased Treg infiltration of the tumor was independent of TGFβ signaling, suggesting a systemic distribution of CXCL8 and IL6 produced by cancer cells, which results in increased neutrophil production, Foxp3 upregulation on T lymphocytes, and tumor trafficking through CXCR1." (PMID 39409924, 2024). "Recently, reports have demonstrated that FoxP3 was also expressed in tumor cells, suggesting that FoxP3 might have a broader role in cancers." (PMID 39073490, 2024). "On the genetic level, our objective was to determine whether rosmarinic acid and doxorubicin could alter the expression of FOXP3, potentially impacting the tumor’s ability to evade immune surveillance." (PMID 39770446, 2024). "This shift to a positive immune equilibrium was further confirmed by polychromatic immunofluorescence staining analysis, as displayed by the spatial distribution of increased CD8 expression and downregulated CD206 and Foxp3 expression within tumor tissues after CISE‐PFD@Gel treatment." (PMID 38884220, 2024). "Mice that received injections of PD-L1 Pep-1 and PD-L1 Pep-2 showed decreased tumour growth and an elevated CD8+/FoxP3+ ratio; however, when peptides and doxorubicin were delivered together via liposomes, the tumour was totally eradicated and the percentage of CD8+ T cells increased dramatically." (PMID 38921739, 2024). "Notably, the Treg percentages and FOXP3 expression in tumor were also lower in cKO mice than in WT mice." (PMID 39446493, 2024). "Ectopic FOXP3 expression inhibits almost all tumor cell types despite the lack of analogous research with the two known X‐linked tumor suppressors." (PMID 38827026, 2024). "During CAC progression, a transient depletion of Foxp3+ Tregs occurs, resulting in tumor growth suppression, while STAT6 signaling may facilitate CAC progression by suppressing the function of Foxp3+ Tregs." (PMID 38892375, 2024). "Therefore, due to the widespread expression of Foxp3 in tumor cells, it has a dual role in tumor induced proliferation or inhibition." (PMID 38919615, 2024). "Treg cells that express the FOXP3 transcription factor play essential roles in immune homeostasis and self-tolerance, which are immunosuppressive and reduce effector T cell proliferation to promote tumor survival." (PMID 38602556, 2024). "Moreover, the frequency of tumor-infiltrating Foxp3+ cells (Treg cells) were significantly reduced in mice treated with trametinib and anti-PD-1 combination." (PMID 38643157, 2024).
tumor (continued). "Additionally, they show increased expression of Foxp3, IDO, cytotoxic effector molecules, and enhanced antigen presentation, along with high tumor mutational burden (TMB) in some cases." (PMID 38785789, 2024). "This could potentially be attributed to the potential of FOXP3 regulatory T cells to obstruct effective anti-tumor immune responses." (PMID 39372398, 2024). "Additionally, another possible explanation is that the ratio of CD25+ or CD25+FOXP3+CD45RA− stromal cell count to CD8+ cell count corresponds to the balance of promoting/inhibiting tumor angiogenesis." (PMID 39232704, 2024). "Foxp3+ Treg accumulation in the tumor microenvironment is an early event along the carcinoma development and may play a role in initiating CRC." (PMID 38343544, 2024). "This difference may be due to a different balance of immune cell subsets within the tumour microenvironment—such a higher abundance of FOXP3 + T-cells, or due to differences in the tumour immune microenvironment such as CTLA-4 expression." (PMID 38649964, 2024). "FoxP3-expressing Treg cells also effectively suppress tumor immunity." (PMID 39150932, 2024). "Studies have confirmed that Foxp3+Treg could be used as a therapeutic target to promote anti-tumor immunity." (PMID 38510491, 2024). "Furthermore, it enhances the maturation of T helper cells into the CD4+CD25+Foxp3+Treg pathways, which can inhibit effector T cell responses and thus reduce anti-tumour immunity." (PMID 39120301, 2024). "A readily achievable initial approach is to confirm the existence of T cells expressing both CD137 and Eomes and/or FoxP3 + within the HPV + OSC microenvironment using in situ analysis of tumor tissue using immunofluorescence (IF) or immunohistochemistry (IHC)." (PMID 38355394, 2024). "However, another study suggested that tumor FOXP3 expression held prognostic value and improved survival outcomes in NSCLC." (PMID 39372398, 2024). "CD4, CD25, and FOXP3 co‐labeled T cell phenotypes were used to assess tumor‐infiltrating Tregs." (PMID 39264227, 2024). "Foxp3, a specific marker for Tregs, plays a critical role in tumor immunity and proliferation." (PMID 39104717, 2024). "Additionally, Foxp3 can control the body’s immunity by directly or indirectly influencing downstream components in tumor cells." (PMID 38919615, 2024). "Tumors may utilize regulatory T-cells (Treg) (CD4/CD25/FOXP3) to create favorable conditions for their development by suppressing the tumor-specific immune response." (PMID 38672662, 2024). "Moreover, Kim’s investigation into the prognostic implications of tumor-infiltrating FoxP3- CD4+ T cells in biliary tract cancer illustrates the critical role of these T cells in CCA." (PMID 39335203, 2024). "The main infiltrating immune cell populations within the GBM microenvironment are tumor-associated macrophages (TAMs), immunosuppressive myeloid-derived suppressor cells (MDSCs), and CD4+CD25+Foxp3+T-regulatory cells (Tregs) that function as tumor growth promoters and induce T-cell dysfunction." (PMID 39267734, 2024). "While HA15 treatment led to substantially reduction of Foxp3+CD4+ Tregs in TME, either the deficiency of IRE1α or XBP1 in tumor cells could partially reverse this alteration." (PMID 38291473, 2024). "Previous reports demonstrated some factors, such as Neuropilin-1 (NRP1) and enhancer of zeste homolog 2 (EZH2), restrictively deleted in Tregs impaired the transcription activity of FOXP3, restricting Treg-suppressive ability and conferring resistance to tumor growth in the host." (PMID 39446493, 2024). "In conclusion, we showed in this study that the infiltration of the tumor area by FoxP3+ Treg and CD45RO+ Tmem cells are highly predictive of late clinical events when they are related to the CD3+ cell population or related to one another using ratio of cell density." (PMID 38887294, 2024).
tumor (continued). "Therefore, we need to further explore and analyze the specific functions of Foxp3+Treg cells in a certain tumor, in order to provide ideas for the treatment of tumors." (PMID 38919615, 2024). "Tumor-infiltrating Tregs exhibit plasticity and have the ability to modify their features to function similarly to effector T cells while maintaining high amounts of FoxP3, known as Th-like Tregs." (PMID 38509593, 2024). "In addition, in EBV-positive CHL, EBV latent antigens modulate the tumor milieu with a heterogeneous population of FOXP3 Treg lymphocytes." (PMID 39200145, 2024). "However, FOXP3‐expressing cells in tumor tissues, a functionally plastic cell population in vivo, confer unregulated properties to T cells." (PMID 39264227, 2024). "Furthermore, castalagin, which is enriched in bacteria associated with effective immunotherapeutic responses (e.g., family Ruminococcaceae and genus Alistipes), improves the ratio of CD8+ cells to FOXP3+CD4+ cells in the tumor microenvironment." (PMID 38803568, 2024). "Also in regard to tumor immunity, several preclinical and clinical studies have suggested that Foxp3 + Treg cells suppress anti-tumor immune responses." (PMID 38402536, 2024). "In the TME, altering Treg function by inducing Treg fragility, with lower expression of FOXP3, enhanced production of tumor-killing cytokines such as interferon-gamma (IFNγ), could contribute to the anti-tumor therapy." (PMID 38167862, 2024). "Since CD8 and FOXP3 were the most prognostic markers in the resections of the previous study, we further explored the spatial heterogeneity for these two markers in the “tumor surface” of the resection." (PMID 39444424, 2024). "This suggests that FOXP3 alone is insufficient as a specific marker of tumor‐infiltrating Tregs." (PMID 39264227, 2024). "In addition, hypoxic environments in the TME increase Treg abundance by upregulating FOXP3, encouraging tumor growth." (PMID 38751938, 2024). "We considered whether gp96-null Tregs retained the ability to migrate into the tumor but converted into so-called Foxp3– “ex-Tregs” in the TME." (PMID 38787791, 2024). "Increased Zn intake was found to facilitate tumor progression by increasing Foxp3+ Treg frequency." (PMID 39247196, 2024). "A high relative difference of ~ 60% was observed for FoxP3 in the B16F10 tumor model." (PMID 38605049, 2024). "In GC tumor tissues, Foxp3 protein is expressed more intracellularly." (PMID 38919615, 2024). "As an active immunotherapy, Mw can activate CD8+ T cells to target DSC3 expressing cancer cells while downregulating tumor induced immunosuppression by decreasing intratumoral FoxP3 and PD-1 expressing immune cells; thus, Mw can be effectively used for management of cancers expressing DSC3." (PMID 39534596, 2024). "Interestingly, tumor-infiltrating Th1 cells (IFN-γ+ TNF-α+ CD4+ T cells) were found to be increased in the DT-mediated Foxp3+ Treg-ablated group in comparison to the control." (PMID 39247196, 2024). "In preclinical models, genetic deletion of VISTA or treatment with anti-VISTA mAb delayed tumor regression by inducing DC maturation, reducing the abundance of adaptive Foxp3+ Tregs, reducing the abundance of MDSCs, and augmenting the effector function and abundance of CTLs." (PMID 37928556, 2023). "Furthermore, the infiltration density of CD8+ TIL, CD4+ TIL, and Foxp3+ TIL in liver metastases was also significantly decreased compared to the primary tumor." (PMID 37828574, 2023). "ESCC has been shown to harbor tumor-infiltrating Foxp3+CD4+ regulatory T cells (Tregs)." (PMID 37275884, 2023). "Chemotherapy might be more effective in tumors with high levels of FOXP3+ TILs, and this in turn could facilitate tumor attack by CD8+ TILs and help to achieve pCR." (PMID 37835488, 2023). "The presence of CD8+ T cells expressing inhibitory markers such as LAG3, TIGIT, KLRC1, and PD-1, and FOXP3+ regulatory CD4+ T cells may prevent effective T cell–mediated tumor control in PDAC." (PMID 37751306, 2023).